IL6 (interleukin 6)
Diseases named in the same sentence as IL6 in open-access papers (continued):
Sharing a sentence is not in itself a finding about the gene and the disease.
tumor (continued). "To further demonstrate PD-1/Al@OV’s ability to modulate the immune microenvironment, we measured tumor-secreted IL-1β, IL-6, and IFN-γ levels using ELISA." (PMID 39955603, 2025). "In contrast, a BMI >25, a pT3 tumor stage, and D.m. type 2 are potentially unfavorable factors increasing IL6." (PMID 40523922, 2025). "In renal cell carcinoma, Ruxolitinib suppresses tumor cell proliferation and survival by inhibiting the IL-6/JAK/STAT signaling pathway and downregulating PIM1 expression." (PMID 40909292, 2025). "M1 macrophages are believed to be pro-inflammatory.They can secrete high levels of pro-inflammatory cytokines (such as TNF-α, IL-1, IL-6, IL-23, etc.), enhance the microbicidal activity, and play an important role in anti-tumor immunity." (PMID 40703527, 2025). "In vivo studies demonstrated that palonosetron reduced tumor growth and modulated pro-inflammatory cytokines—tumor necrosis factor alpha, interleukin 6, and interleukin 1β." (PMID 41155333, 2025). "Firstly, in terms of promoting tumor cell proliferation, IL-6 binds to its receptor on cancer cells, activating the JAK/STAT3 signaling pathway." (PMID 39980561, 2025). "In this B-cell lymphoma subtype, IκBζ is constitutively expressed, leading to an increased expression of IL-6 and IL-10, which in turn enhance tumor growth and survival." (PMID 40562773, 2025). "Meanwhile, granulocyte-macrophage colony-stimulating factor (GM-CSF), granulocyte colony-stimulating factor (G-CSF) and interleukin-6 (IL-6) produced by tumor cells promote the generation of myeloid-derived suppressor cells (MDSCs)." (PMID 40630133, 2025). "M-CSF and IL-6 also play roles in promoting macrophage activity and inflammation, which can influence tumor progression." (PMID 40109854, 2025). "Genetic variants in the IL-6 promoter (e.g., IL6-174C>G) have been linked to increased CRC risk and influence tumor behavior." (PMID 40725273, 2025). "Elevated IL6 in ascitic fluid further suppresses the anti-tumoral immune response and contributes to the tumor progression." (PMID 40427188, 2025). "Curcumin reduced phosphorylation of STAT3 by downregulating IL6 expression, thereby diminishing the proliferation and anti-apoptotic capabilities of tumor." (PMID 40535567, 2025). "Tumor progression is regulated by various pro-inflammatory, such as interleukin (IL)-6 or TNF-α, and anti-inflammatory factors, such as IL-10 and TGF-β." (PMID 39834867, 2025). "The relevance of the connection between inflammation and tumors is also reflected by high IL-6 levels in the tumor microenvironment." (PMID 40699630, 2025). "We investigated the differential expression of IL6 between peri-tumor infiltrating adipose tissue and contralateral adipose tissue in HFD mouse." (PMID 40841364, 2025). "Possible mechanisms include tumor-related secretion of pro-inflammatory cytokines like IL-6 or catecholamine-mediated bone marrow stimulation." (PMID 41477390, 2025). "Recent studies show that supplementation with aronia products can improve inflammatory markers such as interleukin-6 and tumor necrosis factor alpha, highlighting its potential role in modulating the tumor microenvironment." (PMID 41515306, 2025). "Another important aspect of pRb associated with tumour initiation and growth, cytokine regulation and research links pRb inactivation with increased secretion of pro-inflammatory cytokines like IL-6,43 thus establishing an inflammatory tumour microenvironment." (PMID 40331509, 2025). "IL-6 is an important tumor-initiating factor in CRC, and the proliferative and survival effects of IL-6 are primarily mediated by the downstream transcription factor STAT3 36, which is the forward feedback loop of STAT3 that promotes cancer malignancy." (PMID 41281755, 2025).
tumor (continued). "Tumor-derived cytokines and growth factors (e.g., IL-6, GM-CSF, G-CSF, IL-1β, and VEGF) skew hematopoiesis toward stress myelopoiesis and expansion of immature neutrophil and monocyte populations that acquire myeloid-derived suppressor cell (MDSC) phenotypes." (PMID 41463208, 2025). "When the semi-quantitative IRS values were compared between tumour tissues and the corresponding margins, TNF-α, IFN-γ, IL-12 and IL-2 showed relatively lower expression in tumours, whereas IL-1β and IL-6 were elevated in tumour tissue." (PMID 41465261, 2025). "IL-6 secretion activates the STAT3 signaling pathway in tumor cells, promoting survival, proliferation, and resistance to Deoxyribonucleic Acid (DNA)-damaging agents, such as cisplatin." (PMID 40940809, 2025). "IL‐6 has also been reported to influence the tumor immune microenvironment by promoting the induction of suppressive immune cells, such as regulatory T cells (Tregs) and MDSCs, thereby facilitating cancer progression." (PMID 41189442, 2025). "Under thermal stress, the IL-6 level elevates, and its trans-signaling mechanism enhances lymphocyte homing to tumor sites in cancer patients and mice, signifying the bioavailability of IL-6 during acute inflammation or initial phases of infection." (PMID 41376623, 2025). "Broadly, IL-6 favors tumor progression and amongst other functions, promotes angiogenesis and suppresses anti-tumor immunity." (PMID 40760075, 2025). "Steroids and IL-6 blocking for prevention were thought to be counterproductive because they would suppress the anti-tumor effects of CAR T cells, however, this has recently been shown not to be the case when using anti-IL-1 or anti-IL-6 treatment." (PMID 40052127, 2025). "CAFs have facilitated tumor cell migration in vitro and promote lung metastasis in vivo by secreting elevated levels of IL6." (PMID 40344411, 2025). "The transcriptional data obtained from TCGA validated a direct association between IL-6 mRNA levels and PD-L1 expression in ESCC tumor tissues, and it was further validated by immunohistochemistry on ESCC TMAs." (PMID 40433391, 2025). "CAFs secrete various growth factors and cytokines, such as interleukin-6 (IL-6) and IL-8, which remodel the microenvironment and promote tumor growth, invasion, and metastasis." (PMID 41007358, 2025). "Interleukin-6 (IL-6) and interleukin-8 (IL-8) are cytokines that play crucial roles in immune responses, inflammation, and tumor biology." (PMID 40573301, 2025). "IDO1 downregulates IFN-γ and upregulates IL-6, thereby promoting angiogenesis and facilitating tumor growth." (PMID 41035912, 2025). "This lactate-IL-6 axis fosters an immunosuppressive tumor microenvironment and facilitates PDAC progression." (PMID 41152975, 2025). "Higher IL‐6 and GDF‐15 levels were also associated with higher tumour stages (both p < 0.01), positive lymph nodes (p = 0.02 and p < 0.01) and unfavourable surgical margins (both p < 0.01)." (PMID 41380167, 2025). "All OC‐CM treatments increased IL‐6 secretion compared to controls, suggesting that IL‐6 secretion is primarily driven by tumor‐derived factors." (PMID 40255916, 2025). "In accordance with the tumor-immune contexture theory, IL-6 promotes the establishment of an immunologically dysregulated microenvironment that impairs the recruitment, expansion and activation of effector T cells, both locally and systemically." (PMID 41019062, 2025). "The presentation of tumor-specific epitopes to DCs or macrophages triggers the release of inflammatory cytokines, such as IL-1β, IL-6, IL-12, and TNF-α, and the upregulation of CD80/86, which induces the formation of specific Th-1 cells and DC maturation." (PMID 41375025, 2025). "For example, secretion of VEGFA promotes angiogenesis and tumor growth, IL6 activates the STAT/JAK1 pathway enhancing cancer cell plasticity, and TGF‐β induces EMT, cell invasion capacity and resistance to treatment." (PMID 40411295, 2025).
tumor (continued). "Tumor-associated macrophages, an essential component of immune cells in TME, can secrete many pro-inflammatory cytokines, TNF-α, TGF-β, IL-1, IL-6, and IL-12, to enhance the immune response." (PMID 40352594, 2025). "In OC-bearing mice treated with cisplatin, FMT restored microbial balance, reduced tumor burden, repaired intestinal damage, decreased IL-6, and re-sensitized tumors to chemotherapy." (PMID 41294866, 2025). "This bacterium secretes various cytokines, including IL-6, IL-8, TNF-α, and MCP-1, which induce chemotaxis and activate tumor-associated neutrophils." (PMID 39814702, 2025). "On one hand, tumor cells secrete cytokines such as IL-10, IL-6, and IL-17 to induce the differentiation of macrophages into the M2 phenotype." (PMID 41041337, 2025). "IL-6 can be produced by numerous stromal cells including CAFs, in addition to tumor cells themselves, and both paracrine and autocrine activation of the IL-6/JAK/STAT3 pathway in tumors has been reported." (PMID 40597443, 2025). "Alpha 1-acid glycoprotein (AGP) activates TLR4 through CD14, modulating PD-L1 expression and IL-6 production, thus enhancing tumor immune suppression." (PMID 40948759, 2025). "In the view of the significance of IL-6/sIL-6R trans-signaling in tumor progression, targeting this trans-signaling has therapeutic potential." (PMID 40141175, 2025). "IL6 signaling from macrophages in the tumor microenvironment can initiate the common HH-IL6 target gene promoter binding through GLI and STAT3." (PMID 39919692, 2025). "Future research should focus on understanding the spatiotemporal dynamics of IL6 during tumor progression and identifying patient subgroups that would benefit most from IL6-targeted therapies, especially in combination with immune checkpoint inhibitors." (PMID 40427188, 2025). "Among these, IL-6 is particularly significant due to its multifunctional nature and high expression levels within the lung cancer tumor microenvironment." (PMID 41394878, 2025). "Mechanistically, APS co-administration enhanced CD8+ T-cell infiltration, increased splenic and thymic indices, modulated cytokine profiles (TNF-α, IL-2, IFN-γ, IL-12, IL-6, IL-10), and reduced PD-1/PD-L1 expression in tumor tissue." (PMID 41487528, 2025). "TAMs enhance PD-L1 expression via tumor-derived factors such as IL-6, granulocyte-macrophage colony-stimulating factor (GM-CSF), and hypoxia-induced hypoxia-inducible factor 1α (HIF-1α) signaling." (PMID 40177538, 2025). "Ghrelin, in particular, is implicated in tumor advancement and reduced survival rates, while leptin is known to stimulate the production of pro-inflammatory cytokines TNF-α and IL-6, thereby facilitating cancer cell proliferation." (PMID 39980544, 2025). "In cancer, IL-6 can either be pro- or anti-inflammatory depending on the context and can thus demonstrate pro- or anti-tumor effects." (PMID 40094000, 2025). "Another pro-inflammatory cytokine, interleukin-6 (IL-6), is known to promote tumor development, metastasize, and prevent therapy." (PMID 40008130, 2025). "IL-6 is a pleiotropic cytokine that plays a critical role in various physiological and pathological processes, particularly in the tumor microenvironment, where it promotes tumorigenesis and progression by activating the JAK/STAT3 signaling pathway." (PMID 40909292, 2025). "This leads to an increase in the levels of IL-6 in the tumor microenvironment, and by activating the signal transducer and activator of the transcription 3 (STAT3) signaling pathway, it confers upon macrophages the ability to promote tumor growth." (PMID 40563450, 2025). "IL6, produced by multiple cell types, including activated T cells, macrophages, and fibroblasts, plays a role in tumor immunity regulation." (PMID 40678806, 2025). "Liposarcoma‐derived extracellular vesicles carrying miR‐25‐3p and miR‐92a‐3p stimulate TAMs via TLR7/8, triggering IL‐6 secretion that enhances tumor proliferation, invasion, and metastasis." (PMID 41357670, 2025).
tumor (continued). "Agrin promotes immune evasion and tumor growth by stimulating regulatory T-cells and increasing interleukin-6 secretion." (PMID 40584122, 2025). "These protein kinases we identified being activated in OS EV–primed LFs are also known drivers of the secretion of key tumor-promoting cytokines and chemokines such as IL-6, IL-8, and CCL2 across a range of cell types, including fibroblasts." (PMID 40099972, 2025). "Through IL-6R-mediated pathways, IL-6 has the potential to promote angiogenesis as well as tumor growth and progression." (PMID 39941858, 2025). "In Type II EOC, the “hot” immunophenotype of OC, particularly HGSC, IL6 is aggressively involved in driving immune evasion and tumor progression, such as upregulating immune checkpoint molecules, including PD1 and CTLA4." (PMID 40427188, 2025). "CAFs also secrete IL-6, which promotes tumor cells proliferation and invasion through multiple mechanisms." (PMID 40909292, 2025). "Given that there are multiple pro-tumorigenic inflammatory cytokines signaling in the PCa tumor microenvironment, including IL-6, we wanted to determine if chronic IL-1 exposure alters cell response to other cytokines." (PMID 41374981, 2025). "These exosomes significantly increased T-cell infiltration and cytokine expression IL-6, IL-12, and IL-1β within tumors, leading to inhibited tumor progression." (PMID 40103824, 2025). "To verify the safety of EA in tumor treatment, we used ELISA to detect circulating inflammation cytokines IL-6, TNFα and TGFβ, which significantly contribute to tumor progression." (PMID 40475010, 2025). "Recent studies suggest that targeting TAMs-associated pathways, such as the IL-6/interleukin-8 (IL-8) axis or lactate-monocarboxylate transporter-hypoxia-inducible factor 1 alpha (HIF1α) signaling pathway, could reprogram macrophages and disrupt their pro-tumor activities." (PMID 40098971, 2025). "Critically, neurons primed by acid-stressed MSC secretome amplified tumour viability in an IL-6-dependent manner, underscoring the central role of IL-6 in the axonogenesis induced by MSC of OS stroma." (PMID 41029717, 2025). "IL-6 stimulates tumor cell proliferation and survival via JAK/STAT3 signaling and contributes to immunosuppression." (PMID 40746533, 2025). "Tumor tissue samples were used to assess the gene expression of IL-6 and IL-23 by quantitative real-time polymerase chain reaction (qRT-PCR)." (PMID 40612845, 2025). "Parallel TLR5 signaling through the MyD88/TRAF6 complex elevates IL-6 production and induces galectin-1 secretion via myeloid-derived suppressor cells (MDSCs) and γδ T cells, collectively fostering tumor progression." (PMID 40732683, 2025). "For instance, tumor cell-intrinsic TIM-3 stimulates the growth of liver cancer cells via the NFκB/IL-6/STAT3 signaling pathway." (PMID 40332725, 2025). "In prostate cancer lacking PTEN, activated JAK2/STAT3 signaling established an immunosuppressive tumor microenvironment via SASP factors such as CXCL1, CXCL2, and IL-6 and resulted in tumor growth and chemoresistance." (PMID 40862837, 2025). "Beyond its anti-tumor effects, cordycepin exhibits robust anti-inflammatory properties by downregulating pro-inflammatory cytokines, such as IL-6 and TNF-α, which are often elevated in both skin cancer and inflammatory skin disorders." (PMID 39852004, 2025). "By producing mediators such as chondroitin sulfate, TNF, IL-1, and IL-6, it increases inflammatory response and induces apoptosis in tumor cells." (PMID 40244052, 2025). "IL6 plays a significant role in promoting the “cold tumor” phenotype through immune suppression by the expansion of certain immune cells (such as Tregs) and inhibition of others (such as CTL)." (PMID 40427188, 2025). "Tumor cells secrete parathyroid hormone-related protein (PTHrP), interleukin-6 (IL-6), and interleukin-11 (IL-11), which stimulate osteoclast differentiation and activity." (PMID 40426987, 2025).
tumor (continued). "Interleukin-6 (IL-6) and interleukin-8 (IL-8) are pro-inflammatory cytokines crucial to cancer progression, promoting tumor growth, survival, and angiogenesis." (PMID 39861135, 2025). "Although IL-6 is a marker of M1 macrophages with antitumor function, it can be expressed in a number of other cells within the tumor microenvironment, including tumor-infiltrating immune cells, stromal cells, and tumor cells themselves." (PMID 40918453, 2025). "Tumor-related factors include inflammatory cytokines secreted by tumors, such as interleukin-6 (IL-6) and tumor necrosis factor-α (TNF-α), which activate the ubiquitin–proteasome system (UPS), accelerating muscle protein degradation." (PMID 41487675, 2025). "IL-6 has been shown to promote tumor progression through the accumulation of myeloid-derived suppressor cells (MDSCs)." (PMID 40632185, 2025). "In response, tumor cells secrete cytokines such as IL-1, IL-6 and TNF-α and growth factors including TGF-β1 and platelet-derived growth factor BB (PDGF-BB)." (PMID 39020414, 2024). "It is described that in cancer conditions, IL-6 enhances PD-L1 expression in monocytes and IL-6 trans-signaling limits the classical pathway, resulting in increased angiogenesis, tumor growth, and metastasis." (PMID 38790920, 2024). "IL-6 can contribute to tumor growth by up-regulating anti-apoptotic genes and promoting cell proliferation via a STAT-dependent pathway." (PMID 39744628, 2024). "IL-6 also plays an important role in the maintenance of stem/progenitor cells, diffusing through the cellular structures and tissues of the tumor microenvironment due to its low molecular weight." (PMID 38926454, 2024). "For example, IL-6 fuels inflammation and aids tumor progression by activating signaling pathways like Janus kinase/signal transducers and activators of transcription 3 (JAK/STAT3)." (PMID 39449800, 2024). "Elevated circulating IL‐6 is associated with PDAC cachexia in patients and mice, and prior work showed restored ketogenesis in tumour‐bearing mice treated with IL‐6‐neutralizing antibody." (PMID 38632714, 2024). "IL-6 also exhibits significant pro-tumorigenic activity, impacting bone metabolism, tumor cell proliferation and survival, angiogenesis, and inflammation." (PMID 38940936, 2024). "IL-6 and IL-8 can create a chronic inflammatory microenvironment that allows tumor cells to grow and proliferate through direct and/or indirect effects, including cell–cell interactions or cytokine secretion." (PMID 38540708, 2024). "IL-11 is known to stimulate proinflammatory responses, including IL-6 and IL-33, through the JAK–STAT pathway in tissue fibroblasts, of which cancer-associated fibroblasts contribute centrally to the tumor microenvironment." (PMID 39329890, 2024). "The results showed that the primary tumor microenvironment was significantly enriched with various tumor-related pathways, such as TNFα/NFκB-signaling and IL6-JAK-STAT3-signaling." (PMID 39323622, 2024). "IL-6, produced by tumor cells and surrounding stromal and immune cells, is critical in this context." (PMID 39766056, 2024). "IL-6 is upregulated in a variety of malignant tumors and plays a vital role in tumorigenesis and development by influencing tumor cell survival, proliferation, angiogenesis, invasiveness, and metastasis." (PMID 38304429, 2024). "And in our scRNA data, we similarly found that IL-6 was secreted by myeloid cells, especially within tumor tissue." (PMID 38424624, 2024). "IL-6 plays an essential regulatory role among the cytokines secreted by macrophages in promoting tumor progression." (PMID 39247822, 2024). "Some inflammatory factors in the tumor microenvironment, such as interleukin-6 (IL-6), play important roles in the occurrence, progression, invasion, and metastasis of tumors." (PMID 39619013, 2024). "The reduction of IL-6 production by mesothelial cells reduced the growth advantage of Jag2OE tumor cells." (PMID 38575576, 2024).